KRAS (KRas proto-oncogene, GTPase)
Diseases named in the same sentence as KRAS in open-access papers (continued):
Sharing a sentence is not in itself a finding about the gene and the disease.
lung cancer (continued). "Similarly, treatment of KRAS mutant lung cancer with MAPK pathway inhibitors induced IFN-regulated genes including CXCL10 and TNF48." (PMID 34001994, 2021). "XPO1 inhibitors are promising therapeutic strategies in KRAS-mutant lung cancer." (PMID 34299277, 2021). "Thus, combined PLK1/FGFR1 inhibition abolishes ROS homeostasis, leading to oxidative stress‐activated JNK/p38/E2F1 signaling and induction of apoptosis in KRAS‐mutant lung cancer cells." (PMID 34369083, 2021). "Interestingly, in KRAS chemoresistant lung cancer tissues from human patients, high abundance of miR-146 and miR-210 were found compared to non-KRAS metastatic samples." (PMID 34440422, 2021). "Smoking history significantly increases the chance to detect KRAS mutation in lung cancer, regardless of pack-years of smoking." (PMID 33807876, 2021). "EMT also plays important roles in the carcinogenesis of KRAS mutant lung cancer." (PMID 34680229, 2021). "The authors propose that pharmacologic targeting of IL-22 may have potential as an add-on therapy to conventional treatments of KRAS-mutant lung cancer." (PMID 33692792, 2021). "We focused on the treatment effects of verteporfin in KRAS-mutant lung cancer cells." (PMID 33830081, 2021). "Therefore, we concluded that KRAS-mutant lung cancer cells were more receptive to modulation of OPN expression by RESV than EGFR-mutant lung cancer cells." (PMID 33652978, 2021). "All of the clinically-relevant variants of the EGFR, ALK, BRAF and KRAS genes are unambiguously lung cancer-associated and do not meet CHIP criteria; therefore, the presence of CHIP-associated variants doesn’t affect clinical decision making." (PMID 34031447, 2021). "In addition, there were reports that KRAS-driven lung cancer often inactivated STK11/LKB1 and responded poorly to immunotherapy." (PMID 34239621, 2021). "In conclusion, the innovation of traditional treatment strategies and the emergence of new promising drugs may change the treatment pattern of KRAS mutant lung cancer." (PMID 35070984, 2021). "In summary, SDPR could be a promising prognostic factor and potential target for the treatment of lung cancer, especially for KRAS-mutant adenocarcinomas." (PMID 33435990, 2021). "However, no study has reported on the role of melatonin in Hippo-YAP signaling for treatment of KRAS-mutant lung cancer." (PMID 34073318, 2021). "We performed small-molecule library screening and identified verteporfin, a yes-associated protein 1 (YAP1) inhibitor; verteporfin treatment markedly reduced cell viability in KRAS-mutant lung cancer cells in vitro and suppressed KRAS-driven lung tumorigenesis in vivo." (PMID 33830081, 2021). "Furthermore, opposite effects were observed on OPN expression in two KRAS-mutant lung cancer cell lines when PRI-2191 was added to RESV." (PMID 33652978, 2021). "Elevated TGF-β was also found to upregulate FBP1 in KRAS-mutant lung cancer." (PMID 33995422, 2021).
lung cancer (continued). "Moreover, it has been shown to efficiently reduce the viability of several human lung cancer cells in a dose-dependent and KRAS-dependent manner." (PMID 34947990, 2021). "Therefore, we assumed that the inhibitory effects of verteporfin in KRAS-mutant lung cancer cell proliferation were related to EMT-related mechanisms, but we did not observe a clear relationship between the effects of verteporfin and EMT in this study." (PMID 33830081, 2021). "This unique feature of the KRAS G12C mutation has led to the development of specific KRASG12C irreversible inhibitors such us adagrasib and sotorasib which is currently FDA approved to treat patients with KRASG12C lung cancer." (PMID 35004309, 2021). "Furthermore, loss of LKB1 can also promote glutaminolysis and the activation of the TCA cycle, partly mediated by NRF2 in KRAS mutant lung cancer." (PMID 34680229, 2021). "While these reports indicate that different KRAS mutant alleles can contribute to the heterogeneity of KRAS mutant cancers, specific KRAS alleles have not been consistently associated with a subtype of KRAS mutant lung cancer." (PMID 34680229, 2021). "Similarly, other studies have demonstrated the predictive role of KRAS alteration for the treatment of lung cancer." (PMID 34834557, 2021). "As of May 28, 2021, sotorasib has achieved US FDA approval for patients with KRAS G12C mutant lung cancer after one line of a prior therapy." (PMID 34845311, 2021). "Consistent with this hypothesis, siRNAs knockdown of KRAS greatly reduced cytoplasmic EZH2 in A549 cells, which have mutant KRAS, and increased DLC1 protein in A549 and four other lung cancer lines with mutant KRAS." (PMID 34862367, 2021). "A KRAS-targeting peptide vaccine has been engineered to prevent lung cancer." (PMID 33869008, 2021). "IHC staining showed that LKB1 loss increased the global 5-mC DNA methylation in lung cancer tissues with KRAS mutations, but not in tissues with WT KRAS." (PMID 34016959, 2021). "In general, previous studies based on patients with lung cancer from Xuanwei/Qujing showed that a higher proportion of EGFR compound mutations and KRAS mutations were observed, although EGFR mutation rate in patients with lung cancer patients from Xuanwei was still controversial." (PMID 33928034, 2021). "As a control, we used two lung cancer-derived cell lines, A549 (homozygous KRAS G12S mutation; KRAS non-addicted) and H358 (heterozygous KRAS G12C mutation; KRAS-addicted), and melanoma-derived cell line, A375 (homozygous BRAF V600E mutation; BRAF-addicted)." (PMID 33793658, 2021). "In addition, KRAS mutation is also frequency found in lung adenocarcinoma, blocking of autophagy under suppressing of KRAS activity can elevate cytotoxicity of lung cancer cells." (PMID 34576028, 2021). "This study reports a synergistic drug combination by targeting FGFR1 and PLK1 and identifies autophagy as a protective mechanism that limits the efficacy of FGFR1/PLK1 inhibitor therapy in KRAS‐mutant lung cancer, suggesting a novel strategy to treat the daunting disease." (PMID 34369083, 2021). "Similarly, MEK inhibition in KRAS-mutant lung cancer A549 cells and BRAF inhibition in BRAF-mutant melanoma A375 cells also increased IRF1 and IFIT1 protein levels (right)." (PMID 34535668, 2021). "EGFR gene mutations are seen in up to 40% of never smoker, compared to 1% in the smoker, while KRAS mutation is almost exclusively limited to smoker’s lung cancer." (PMID 34181354, 2021). "Identification of verteporfin as a cytotoxic agent in KRAS-mutant lung cancer cells." (PMID 33830081, 2021). "Inactivation of MAP2K7 in KRAS-driven lung cancer accelerates tumorigenesis and reduces survival." (PMID 34616731, 2021). "Therapeutic targeting of mutant KRAS lung cancers remains an unmet clinical need." (PMID 34068816, 2021).
lung cancer (continued). "The continued study of targeting a specific vulnerability of KRAS-mutant lung cancer cells may provide new insights for therapeutic intervention that warrant further investigation." (PMID 33830081, 2021). "MET exon 14 skipping mutation occurs in approximately 3% of lung adenocarcinoma and 2.3% of other lung cancer subtypes and is mutually exclusive with other known driver gene mutations such as EGFR, KRAS, and HER2, suggesting its potential as a true oncogenic driver site." (PMID 34660325, 2021). "Thus, EGFR-mutant lung cancer cells are more sensitive to the anti-proliferative effects of vitamin D in contrast to KRAS-mutant lung cancer cells." (PMID 33652978, 2021). "Among these mutations, KrasG12D is found in ~15% of KRAS-mutant lung cancer cases, and more than half of never-smoking lung cancer patients have the KrasG12D mutation." (PMID 34635780, 2021). "However, to date only a limited number of studies addressed KRAS-related molecules in KRAS-driven or KRAS harbouring lung cancer, specifically with the use of CRISPR/Cas systems." (PMID 34781949, 2021). "Moreover, KRAS mutant lung cancer cells are sensitive to ferroptosis induced by the inhibition of SLC7A11." (PMID 34742351, 2021). "Furthermore, cell death was triggered in transfected cells, since colorectal and lung cancer cells are KRAS dependent." (PMID 34781949, 2021). "To date, there have been limited reports on CRISPR applications in targeting KRAS in lung cancer." (PMID 34781949, 2021). "Moreover, the combination failed to activate the p38/JNK‐E2F1 axis and induce apoptosis, but successfully evoked autophagy (LC3‐II expression) in EBC‐1 cells, in contrast to the scenario observed in KRAS‐mutant lung cancer cells." (PMID 34369083, 2021). "Moreover, combined insulin-like growth factor 1 receptor (IGF1R) and MEK blockade showed significant effects in KRAS-mutant lung cancer cells and in KRAS-driven mice tumor models." (PMID 34301278, 2021). "Moreover, systematic exploration of SDPR in gene location, species conservation, function, and potential regulatory network was illustrated in lung cancer, especially in KRAS-mutant tumors." (PMID 33435990, 2021). "However, it is intriguing that ML111 potently inhibited the EML4-ALK fusion-driven H3122 and KRAS/PI3KCA-mutant H460 lung cancer cell lines." (PMID 34683845, 2021). "From a genetic perspective, data retrieved from the COSMIC database suggest that KRAS mutant lung cancer models lack the WT copy of the gene more frequently than other tumor types and such homozygous alterations are mostly seen in cell lines harboring G12C and G12V mutations." (PMID 34573384, 2021). "This study evaluated KRAS targeting by these PEGylated ASOs in lung cancer." (PMID 33740988, 2021). "The failure of MEK inhibitors against KRAS mutant lung cancers and the low percentage of sustained durable responses with anti-PD-1/PD-L1 immune checkpoint blockade therapies emphasize the need to understand drug resistance mechanisms to improve patient survival." (PMID 33972557, 2021). "To this end, in this study, we investigated whether BLT2 contributes to mutant KRAS-driven lung cancer progression." (PMID 34635780, 2021). "Lung cancer patients with this tumor genetic profile showed a worse response to ICI than did patients with KRAS-mutant tumors without LKB1 co-mutations." (PMID 35096591, 2021).
lung cancer (continued). "Here the authors show that deubiquitinase USP12 downregulation contributes to development of an immune-suppressive tumour microenvironment in KRAS-driven lung cancers and mechanistically this is through the insufficient deubiquitination of the NF-κB inhibitor, PPM1B." (PMID 34381028, 2021). "Among them, KRAS, which is frequently mutated in lung cancer, and EGFR, which is a major therapeutic target in this disease, were also predicted targets of three miRNAs identified in EBC from lung cancer patients." (PMID 33572343, 2021). "To investigate the gene expression signature in KRAS-oncogene-driven lung cancer, we compared the differences between KRAS-mutant tumors and normal lung tissue derived from a genetically engineered mouse model (GEMM), based on expression profiling and comprehensive bioinformatics analysis." (PMID 33435990, 2021). "In contrast, the lung adenocarcinoma tissue sections showed positive staining for KrasG12D, and the KrasG12D-stained samples showed high BLT2 expression in the KrasG12D-positive region, consistent with the suggested role of elevated BLT2 expression in KRAS-driven lung cancer." (PMID 34635780, 2021). "As expected, BKA-073 significantly reduced tumor burden in the lungs of KL mice leading to prolonged survival when compared with the untreated control group, suggesting that BKA-073 has the potential to improve the prognosis of patients with mutant KRAS-driven lung cancer." (PMID 34373755, 2021). "In KRAS-driven lung cancer, the IKKβ-depleted mice showed enhanced tumorigenesis." (PMID 34885082, 2021). "We aim to summarize the tumor heterogeneity of KRAS mutant lung cancers and its immune-regulatory role, to report the efficacy achieved with current immunotherapies, and to overview the therapeutic approaches targeting KRAS mutations besides KRAS G12C inhibitors." (PMID 35096591, 2021). "Interestingly, FGFR1 also mediates adaptive resistance to MEK inhibitors in KRAS-mutant lung cancer cells." (PMID 34858498, 2021). "Finally, we only carried out experiments using A549 cells, which acted as surrogate tissue for KRAS mutant/EGFR wild type lung carcinoma." (PMID 34858801, 2021). "Further evidence for the potential of KRAS-G12C inhibition to reduce the immunosuppressive tumour microenvironment produced by oncogenic KRAS and potentially sensitise tumours to immune checkpoint blockade came from another study using the 3LL ΔNRAS murine lung carcinoma line." (PMID 34200676, 2021). "Such oncogenic forms of the KRAS gene are prevalent in pancreatic carcinomas (>80%), colon carcinomas (40–50%), and lung carcinomas (30–50%), but are also present in biliary tract malignancies, endometrial cancer, cervical cancer, bladder cancer, liver cancer, myeloid leukemia and breast cancer." (PMID 35004317, 2021). "Moreover, knockdown of IDO1 suppressed the metastatic development of cancer cells as demonstrated for KRAS-induced lung carcinoma." (PMID 34769098, 2021). "Moreover, unresolved ER stress induced by a high-calorie diet reduces the tumorigenic potential of mutant KRAS-driven lung cancer, which suggests that ER stress is a potential drug discovery target for KRAS-mutant lung cancer." (PMID 32728173, 2020). "Furthermore, USP18 deubiquitinates and stabilizes Kirsten rat sarcoma viral oncogene homolog (KRAS), thereby leading to the promotion in aggressiveness of lung cancer." (PMID 32957626, 2020). "Furthermore, the reliance of KRAS on Rac1 in lung cancer development also predicts Rac-GEFs as KRAS effectors, also potentially via a PI3K-dependent mechanism." (PMID 32158759, 2020).
lung cancer (continued). "In this study, we systematically investigated the alterations of DMEs in KRAS mice of different ages and sexes, with the aim of providing a better explanation for the clinically observed variation in the efficacy and toxicity of anticancer drugs in KRAS-mutant lung cancer patients." (PMID 33240601, 2020). "Notably, growths of all KRAS-mutant cells (A549, H358, H460, and H1373) were attenuated by PIERCE1 KD, while half of KRAS WT lung cancer cell lines (H3122, H226, HCC827, PC-9, H1299, and Heas-2B) were responsive to PIERCE1 depletion." (PMID 32728173, 2020). "Except for the detection of ERBB2 amplification and KRAS mutation in two patients, no other classic lung cancer driver mutations were detected." (PMID 31659278, 2020). "Interestingly, many lung cancer “driver” genes were highly expressed in the rare epithelial cells, with expression of EGFR and KRAS, the top mutated oncogenes in adenocarcinoma, enriched in ionocytes and neuroendocrine cells, respectively." (PMID 32727470, 2020). "Here, we show, not only that IKKβ activity is increased in KRAS-mutant lung tumourspheres, but also that IKKβ targeting in KRAS-mutant lung cancer cells reduces expression of stem cell factors, as well as KRAS-mutant lung tumoursphere formation and self-renewal." (PMID 32823550, 2020). "Based on this evidence we hypothesized that IKKβ would promote KRAS-driven lung cancer stemness and invasion." (PMID 32823550, 2020). "To date, the most optimal treatment of KRAS‐mutant lung cancer remains controversial." (PMID 31709742, 2020). "We employed an established mouse model of KRAS‐driven lung cancer." (PMID 32037720, 2020). "The combined analyses of PD-L1 and CD8+ TILs showed a significantly higher proportion of dual-positive (PD-L1+/TIL+) patients in the KRAS-mutant group than in the triple wild-type group (P = 0.019), indicating KRAS-mutant lung cancers drove an inflammatory phenotype with adaptive immune resistance." (PMID 32944405, 2020). "Taken together, our results identify IKKβ as an important mediator of KRAS-induced stemness and invasion in lung cancer and indicate that IKKβ inhibition might selectively target cells with stem cell and invasive traits." (PMID 32823550, 2020). "Our results suggest that LPIAT1 may be essential for KRAS-mediated prostaglandin production in lung cancer cells." (PMID 32034305, 2020). "The expression of SULT1A3 should be further explored in KRAS-mutant lung cancer patients." (PMID 33240601, 2020). "Since a synthetic lethal interaction has been reported between KRAS mutants and CDK4, we asked whether expression of cyclin D1 and CDK4 might be associated with the KRAS mutation in lung cancer patients." (PMID 32104498, 2020). "However, to date, it is still a major challenge to develop novel drugs that effectively treat KRAS mutant lung cancer." (PMID 33240601, 2020). "Moreover, the antitumor effect of ER stress against KRAS-mutant lung cancer suggests a potential novel strategy as a therapeutic target for lung cancer." (PMID 32728173, 2020). "Furthermore, we observed that breast cancer metastases at any site that harbor mutations in KEAP1, KRAS, and STK11, a triplet commonly associated with lung cancer, genomically resemble lung tumors (100% vs. 18%, p = 2e-8, n = 13)." (PMID 32374727, 2020). "KRAS is the first driver gene identified in lung cancer patients." (PMID 33255238, 2020). "So, FGL2 affect KRAS by influencing immune status in tumor environment of lung cancer." (PMID 32206449, 2020). "In addition, a recent study has reported that the down-regulation of RAGE by small interfering RNA (siRNA) inhibits migration and invasion through negatively regulating PI3K/AKT and KRAS/RAF-1 signaling cascades in lung cancer H1975 cells." (PMID 32327633, 2020).